STAT3 (signal transducer and activator of transcription 3)
Diseases named in the same sentence as STAT3 in open-access papers (continued):
Sharing a sentence is not in itself a finding about the gene and the disease.
cervical carcinoma (continued). "A study proved that resveratrol inhibited cervical cancer cell proliferation by upregulating suppressors of cytokine signaling 3 (SOCS3) and activated STAT3 (PIAS3) expression, blocking the DNA-binding activity of STAT3 and causing STAT3 inactivation." (PMID 34680171, 2021). "Therefore, STAT3 has become a therapeutic target in a variety of cancers, including bladder, ovarian, and cervical cancers and head and neck squamous cell carcinoma (HNSCC)." (PMID 34445405, 2021). "Moreover, signaling triggered by G-CSF, also expressed by cervical cancer cells, activates STAT3 and has been shown to promote the accumulation of tolerogenic myeloid cells facilitating tumor growth." (PMID 33330068, 2020). "RBM8A is known to be a component of the exon junction complex, which could regulate IL-6-induced STAT3 activation in human cervix carcinoma cell line." (PMID 32294703, 2020). "Both miRNAs negatively correlate with STAT3 expression in cervical cancer cells." (PMID 32899142, 2020). "To confirm whether STAT3 serves as an important modulator of cervical cancer progression, we established a knockdown cell line by using shRNA that targeted STAT3 transcripts and performed colony formation assays." (PMID 32491253, 2020). "HeLa and SiHa cells were treated with RES and S3I201 or AG490, and the expression levels of N‐cadherin, E‐cadherin, vimentin, MMP‐3, and MMP‐13 were examined to confirm that the role of STAT3 phosphorylation was inhibited by RES on the invasion potential of cervical cancer cells." (PMID 33040485, 2020). "This study indicates that STAT3 and NFκB are involved in immunomodulatory tumor effects and STAT3 inhibition could be considered as therapy for patients with cervical cancer." (PMID 33330068, 2020). "Our patients’ data together with experimental evidence that chronic activation of STAT3 promotes tolerance toward cervical cancer antigens led us to investigate if IL-6 and G-CSF could have a role in tumor growth and modulation of tumor systemic effects." (PMID 33330068, 2020). "Findings indicate that STAT3 has a potential role in the development of cervical cancer." (PMID 32527332, 2020). "This active repression may be required to block TWIST1 expression, as STAT3 is activated by HPV in cervical cancer cells, and active STAT3 is an activator of TWIST1 expression, promoting EMT." (PMID 33298572, 2020). "The very clear and significative increase in STAT3 and decrease in NFκB expression in circulating leukocytes not only can evidence the systemic effects of cervical cancer, as actually may have an important biological significance." (PMID 33330068, 2020). "Our results suggest that inhibiting STAT3 may be a useful tool for cervical cancer or high-grade lesions treatment." (PMID 33330068, 2020). "The role of resveratrol(RES)in inhibiting the STAT3 signaling pathway in vivo, particularly in cervical cancer is still unknown." (PMID 33040485, 2020). "Given this information it was pertinent to investigate the consequences of inhibiting STAT3 activation in HPV positive cervical cancer cells by the application of two chemically distinct inhibitors of STAT3 (cryptotanshinone and S3I-201) or by transfecting cells with a pool of STAT3 specific siRNA." (PMID 31226168, 2019). "As STAT3 can be activated by several soluble factors in cervical cancer cells, such as OSM, EGF and IL-10, it is possible that the IL-6 low cancers might be dependent on these additional cytokines to maintain active STAT3." (PMID 31226168, 2019). "We previously demonstrated that the HPV encoded E6 protein increases the activity of the proto-oncogenic transcription factor STAT3 in primary human keratinocytes; however, the molecular basis for STAT3 activation in cervical cancer remains unclear." (PMID 31226168, 2019). "In cervical cancer, miR-125a suppresses tumour growth, invasion and metastasis by targeting STAT3." (PMID 31598146, 2019).
cervical carcinoma (continued). "Crucially, STAT3 activity is essential for the proliferation and survival of cervical cancer cells, suggesting that targeting STAT3 may have therapeutic potential." (PMID 31817106, 2019). "Taken together, targeting the STAT3 signaling pathway using TMS-TMF-4f could be a potential approach in human cervical cancer therapy." (PMID 31816985, 2019). "Furthermore, the contribution of IL-6 to STAT3 activation in cervical cancer remains poorly defined." (PMID 31226168, 2019). "Interestingly, targeting of key upstream factors necessary for the autocrine activation of STAT3 also impaired proliferation indicating that this signalling circuit is essential in cervical cancer cells." (PMID 31226168, 2019). "TMS-TMF-4f treatment could not only induce cell death in cervical cancer cells but also prevent tumor growth in a xenograft cervical cancer model by suppressing STAT3 phosphorylation via the induction of apoptosis." (PMID 31816985, 2019). "We therefore rationalised that inhibition of STAT3 using the clinically approved JAK2 inhibitor ruxolitinib may synergise with cisplatin in inducing cell death in HPV+ cervical cancer cells." (PMID 31817106, 2019). "Moreover, IL-6 can induce the expression of vascular endothelial growth factor via the STAT3 pathway, leading to tumor angiogenesis and thereby promoting the development of cervical cancer." (PMID 31297140, 2019). "Upon STAT3 depletion we observed a marked reduction in the levels of IL-6 mRNA, IL-6 protein expression and secretion, indicating that STAT3 likely drives a mechanism to maintain enhanced IL-6 expression in cervical cancer cells." (PMID 31226168, 2019). "We analysed the level of STAT3 phosphorylation in a panel of six cervical cancer cell lines to establish whether HPV augmentation of STAT3 phosphorylation was evident." (PMID 31226168, 2019). "STAT3 is an important oncogene in cervical cancer occurrence." (PMID 31320837, 2019). "This is important because STAT3 can be over-expressed and constitutively-activated in cervical cancer, and decreasing its expression may help to increase CD8+ cell infiltration to the tumor." (PMID 30283446, 2018). "S1P could serve as a key upstream signal of STAT3 (signal transducer and activator of transcription 3), the latter is a key participant in cervical carcinoma progression." (PMID 29416779, 2018). "For example, Tuberatolide B isolated from the Korean marine algae Sargassum macrocarpum inhibits the proliferation of breast, lung, colon, prostate, and cervical cancer cells by disrupting the signal transducer and activator of transcription 3 (STAT3) signaling pathway." (PMID 29584673, 2018). "Although STAT3 phosphorylation was increased in primary keratinocytes containing HPV18, we queried whether aberrant STAT3 phosphorylation correlated with cervical cancer initiation and progression." (PMID 29630659, 2018). "B-cell CLL/lymphoma 3 (Bcl3) may induce cell proliferation and inhibit cell death as an oncogenic gene by regulating STAT3 in several cancers including cervical cancer, glimo cell." (PMID 29545936, 2018). "Moreover, overexpression of HPGD inhibits proliferation, migration and anchorage-independent growth in cervical cancer cells by inhibiting STAT3 and AKT activation." (PMID 30333561, 2018). "Accordingly, co-staining of the endogenous, non-tagged STAT3 and ATP6V01D, a lysosomally localized subunit of V-ATPase, in fixed and saponin-permeabilized HeLa cervix cancer cells showed less colocalization of STAT3 and lysosomes than observed by live-cell imaging." (PMID 30127373, 2018). "This suggests that the IL-6/JAK/STAT3 signaling pathway might be an interesting target to revert immune deviation in cervical cancer." (PMID 28895886, 2017).
cervical carcinoma (continued). "Collectively, our data suggest that chemotherapy-mediated miR-29b expression participates in the initiation and progression of cervical cancer through suppressing the proliferation, EMT procedure and angiogenesis of cervical cancer cells by targeting STAT3 signal pathway." (PMID 28122338, 2017). "Notably, in invasive cervical cancers STAT3 activation is often retained at the tumor margin adjacent to the stroma, while in other parts of the tumor STAT3 activation declines compared to cervical high-grade lesions." (PMID 28895886, 2017). "To comfier whether the miR-29b/STAT3 axis performs function in cervical cancer, we analyzed the binding ability of miR-29b to wild or mutant STAT3 3′UTR using the dual-luciferase reporter assays." (PMID 28122338, 2017). "It has been reported that activated STAT3 was overexpressed in cervical cancer and could act as a predictor of poor prognosis, suggesting its potential role in progression of cervical carcinogenesis." (PMID 28455960, 2017). "We identified that STAT3 was a functional target gene of miR-29b in cervical cancer cells, and might be involved in the miR-29b axis on cervical cancer chemotherapy of cisplatin." (PMID 28122338, 2017). "In addition, IL-37 has been shown to suppress cell proliferation and invasion of human cervical cancer (CC) and Renal cell carcinoma (Rcc) through inhibiting signal transducer and activator of transcription 3 (STAT3) signaling." (PMID 27835881, 2016). "In terms of mechanism, LYN could also promote cervical cancer cells metastasis through activating IL-6/STAT3 pathway." (PMID 27690342, 2016). "Previously, and consistent with our results, it has been reported that the signaling pathway that involves STAT3 is activated constitutively in cervical cancer, this was observed in vivo on the tissue from patients as well as in vitro on different cell lines derived from cervical cancer." (PMID 26346346, 2015). "In addition, CC cells derived from primary cervical cancers expressed lower levels of STAT3 than the ones derived from metastatic sites." (PMID 26389681, 2015). "Chen and colleagues reported constitutive activation of STAT3 in 22% of 165 cervical cancers." (PMID 25268165, 2014). "Alternatively, the activated STAT3 signaling seems more crucial than the other two in the proliferation and survival of human cervical cancers although Notch signaling may also play certain roles in those processes." (PMID 25061499, 2014). "And STAT3 signaling is constitutively activated in cervical cancer and may play potential role in progression of HPV16-mediated cervical carcinogenesis." (PMID 25061499, 2014). "In view of the fact that E6 is known to activate IL-6/STAT3 signaling in cervical cancer cells, our results demonstrate existence of HPV16 E6-induced proinflammatory signaling that operate through STAT3 and miR-21 by blocking its negative regulators Let-7a and PTEN." (PMID 25539644, 2014). "Implications: miR-21 and Let-7a along with STAT3 may prove useful targets for pharmacological intervention for management of cervical cancer." (PMID 25539644, 2014). "Specific targeting of STAT3 expression in cervical cancer cell lines have been performed earlier using recombinant adenoviral dominant negative STAT3 or STAT3 specific siRNA which invariably demonstrated similar decrease in cell numbers and affected the viability of cervical cancer cells." (PMID 23874455, 2013).
cervical carcinoma (continued). "Therefore our results show that inhibition of STAT3 and loss of E6/E7 culminates in apoptotic cell death in HPV16 positive cervical cancer cells." (PMID 23874455, 2013). "Interestingly, expression of some of these genes such as Bcl-xl, survivin and Mcl-1 have been shown a strong correlation with pSTAT3 levels in cervical lesion and their expression was found abrogated by specific targeting of STAT3 in cervical cancer cells." (PMID 23874455, 2013). "Interestingly, recent study identifying cancer stem-like cells from primary cervical carcinoma also demonstrated high expression of STAT3 mRNA in all of the sphere-forming stem cells." (PMID 20977777, 2010). "Similarly, STAT3 has also been shown to be a poor prognostic factor in cervical cancer by other investigators." (PMID 20977777, 2010). "Similarly, in a recent report, with lower stringency of analysis by considering 10% cells expressing nuclear pSTAT3 as cut off for positives, a maximum of 57% STAT3 positivity was observed in cervical cancer tissues." (PMID 20977777, 2010). "Similarly, a high level of constitutively active STAT3 expression was observed in HPV-positive cervical cancer cell lines when compared to that of HPV-negative cells." (PMID 20977777, 2010). "However, the interaction of HPV16 or its oncogenes with STAT3 signaling in cervical cancer and the mechanism of HPV16-mediated STAT3 activation is yet to be elucidated." (PMID 20977777, 2010). "Indeed, our recent observations do indicate an increased STAT3 mRNA expression in cervical cancers which was also validated in the current study." (PMID 20977777, 2010). "Stat3 targeted therapy seems to be a promising new strategy for the treatment of cervical cancer." (PMID 19638983, 2009). "However, elevated phosphorylation of Stat3 (Tyr705) was detected in HeLa, SiHa, and HT-3 cervical cancer cell lines." (PMID 17311011, 2007). "Stat3 activation in cervical cancer is also largely unclear but one of the mechanisms may be involved in interleukin-6." (PMID 17311011, 2007). "Inhibition of activated Stat3 in early stage(s) of cervical cancer might prevent further progression of cervical cancer." (PMID 17311011, 2007). "Therefore, constitutive activation of Stat3 seems to be one of the common molecular mechanisms to promote oncogenesis in gynecologic cancers including ovarian, endometrial, and cervical cancers." (PMID 17311011, 2007). "Given that Stat3 can contribute to cancer progression and tumour angiogenesis, it is important to explore whether Stat3 is also activated in endometrial and cervical cancers." (PMID 17311011, 2007). "We next examined the phosphorylation of Stat3 (Tyr705) in cervical cancer specimens." (PMID 17311011, 2007).
cervical carcinoma (continued). "The present study investigated the activation Stat3 in endometrial and cervical carcinomas, which should help us to better understand the cancer progression of endometrial and cervical cancers that involve the activation of multiple oncogenic pathways including the constitutive Stat3 pathway." (PMID 17311011, 2007). "Therefore, we examined the Tyr phosphorylation of Stat3 at residue 705 (activated form of Stat3) in human endometrial and cervical cancer tissue microarray slides that contain multiple cancer specimens." (PMID 17311011, 2007). "We propose that targeting the CXCL12‐CXCR4 axis, SNAIL, FOXP3, and its rs3761549 variant in an oncogenic HPV/XPO5 TME—characterized by high M2‐TAM infiltration and STAT3/NF‐κB upregulation—may help counteract immunosuppression and metastasis in cervical cancer." (PMID 41263059, 2025). "Furthermore, STAT3 accelerates drug resistance of cervical cancer cells." (PMID 36793374, 2023). "Hence, in order to explore the relationship between STAT3 and autophagy of cervical cancer cells, the expression levels of autophagy marker proteins (Beclin1, P62, LC3B) in STAT3-KO/sh-STAT3 and relative control cells treated with or without chloroquine were detected by western blotting." (PMID 35057825, 2022). "STAT3 may upregulate the autophagy level of cervical cancer cells through the Bcl2-Beclin1 axis." (PMID 35057825, 2022). "Collectively, our findings demonstrate that the OSM-STAT3 signaling pathway regulates crucial transcriptomic programs through epigenetic changes and that selective inhibition of STAT3 may be a novel therapeutic strategy for patients with advanced cervical cancer." (PMID 36551576, 2022). "However, how STAT3 regulates the autophagy of cervical cancer cells in cervical cancer remains unclear." (PMID 35057825, 2022). "Recently, studies have shown that STAT3 has a significant impact on the proliferation and apoptosis of cervical cancer cells, and mainly plays the role as one of the key oncogenes, promotes the proliferation of cervical cancer cells and inhibits their apoptosis." (PMID 35057825, 2022). "However, the contribution of IL-6 to STAT3 activity in cervical cancer is not well understood." (PMID 34445405, 2021). "Thus, it suggests that the STAT3 gene might be used as a prognostic marker in cervical cancer prognosis at a very primary stage." (PMID 33946372, 2021). "On the other hand, it was seen that miR-411 inhibited the progression of cervical cancer when interacting directly with STAT3; the authors also indicated that this miRNA may represent a new potential therapeutic target and prognostic marker for patients with this disease." (PMID 33803022, 2021). "Thus, it is speculated that PLK1 may also promote lymph node metastasis of cervical cancer by interacting with genes such as STAT3 or regulating certain pathways in cervical cancer." (PMID 33354424, 2020). "Moreover, miR-125a represses tumor growth in cervical cancer through targeting STAT3." (PMID 33185692, 2020). "However, how RES exerts antitumor effects on cervical cancer cells by inhibiting STAT3 phosphorylation in vivo remains unknown." (PMID 33040485, 2020). "Our data showing the opposite expression of STAT3 and p65-NFκB according to lesion grade in peripheral blood leukocytes led us to speculate whether these signaling pathways could be part of the immunomodulatory effects of cervical cancer." (PMID 33330068, 2020). "We discovered that EGF could induce the phosphorylation of STAT3 in HeLa cervical cancer cells." (PMID 31470515, 2019). "Thus, STAT3 is essential for HPV+ cervical cancer cell survival." (PMID 31226168, 2019). "In this study, we evaluated the effect of these synthetic hybrids on the viability of other five human cancer cells and investigated their underlying molecular mechanisms, which may be mediated by the suppression of STAT3 activation in human cervical cancer cells in vitro and in vivo." (PMID 31816985, 2019).